VIM (vimentin)
Diseases named in the same sentence as VIM in open-access papers (continued):
Sharing a sentence is not in itself a finding about the gene and the disease.
liver fibrosis (55 papers, 2012 to 2026). "We reported that hepatocytes extracted exosomes treated with H. pylori-derived OMVs can cause HSC activation and elevate the expression of hepatic fibrosis markers (β-catenin, vimentin, α-SMA, and TIMP-1)." (PMID 37090196, 2023). "The qPCR results showed that the levels of mRNA markers associated with EMT (vimentin) and liver fibrosis (Collagen I, III, and IV) in the liver at 20 days post infection were significantly higher than those in the uninfected group." (PMID 36828540, 2023). "Blocking Notch signaling activation by a γ-secretase inhibitor, DAPT, significantly attenuated liver fibrosis and decreased the expression of snail, vimentin, and TGF-β1 in association with the enhanced expression of E-cadherin." (PMID 23056328, 2012). "Notably, alterations of vimentin expression are linked to diseases including lung and liver fibrosis and several types of cancer, all of which involve cell migration and ECM remodeling." (PMID 35359446, 2022). "In keeping with such roles, identification of the coordinated proteins and molecules modulated by vimentin might reveal the IF-mediated cytoskeleton cross talk associated with liver fibrosis." (PMID 31581522, 2019). "Furthermore, CB1-RNAi-LV ameliorated dimethylnitrosamine induced hepatic fibrosis markedly, which was associated with the decreased expression of mesenchymal cell markers smooth muscle α-actin, vimentin and snail, and the increased expression of epithelial cell marker E-cadherin." (PMID 23251393, 2012). "Hepatic stellate cells, characterized by DES and VIM expressions, are central to liver fibrosis and extracellular matrix remodeling." (PMID 41535358, 2026). "PSR staining and western blotting assays for detecting the expression of α-SMA and Vimentin were conducted to measure the severity of hepatic fibrosis." (PMID 40025174, 2025). "DAPT significantly attenuated hepatic fibrosis and decreased the expression of Snail, vimentin, and TGF‐β1 in association with the enhanced expression of E‐cadherin in rat hepatic fibrosis models." (PMID 39665319, 2025). "Consistently, immunofluorescence microscopy analysis of α-SMA and vimentin, as well as Sirius red staining of liver sections, both demonstrated that loss of IFT88 in HSCs significantly enhanced CCl4-induced liver fibrosis." (PMID 38351372, 2024). "Increased levels of vimentin have been measured in the plasma of patients and rats with liver fibrosis in comparison to healthy subjects." (PMID 39057066, 2024). "Based on the initial analysis, a circRNA derived from exons 4 to 8 of the vimentin (VIM) gene (termed cVIM) was selected for subsequent experiments and its functions and mechanisms of action in liver fibrosis progression were extensively explored." (PMID 38243118, 2024). "The liver fibrosis-specific circRNA was explored by a circRNA microarray and cVIM (a circRNA derived from exons 4 to 8 of the vimentin gene mmu_circ_32994) was selected as the research object." (PMID 38243118, 2024). "Liver injury and severe liver fibrosis were confirmed by routine histology, and immunohistochemistry showed increased vimentin staining in the DMN-treated livers compared to the controls." (PMID 39057066, 2024). "Vimentin is critically involved in liver fibrosis with the scarring of the liver representing defective wound repair." (PMID 39170945, 2024). "As a result, these engineered EVs had high potency to rescue liver function and reduce ECM (collagen I and FN) and vimentin expression in a CCl4-induced liver fibrosis model." (PMID 36341339, 2022). "CCl4 can activate hepatic stellate cells, which can express vimentin in large quantities, and then start the process of liver fibrosis." (PMID 34899319, 2021). "To further verify the role of vimentin in the progression of hepatic fibrosis, we evaluated the levels of vimentin in the clinical plasma specimens obtained from the healthy controls and from subjects with liver fibrosis/cirrhosis." (PMID 31581522, 2019).
liver fibrosis (continued). "Peroxisome proliferator activated receptor-γ (PPARγ), a key regulator in HSC activation and phenotypic alteration, was tested after vimentin silence to assess the potential influence of vimentin on liver fibrosis." (PMID 31581522, 2019). "Again, our results also showed that vimentin was significantly upregulated in the plasma samples obtained from patients with liver fibrosis or cirrhosis compared to those in the control group (p < 0.001)." (PMID 31581522, 2019). "Importantly, vimentin-positive HSCs were identified within mature mHBOs, this resident mesenchymal population is essential for modeling hepatic fibrosis." (PMID 41378211, 2025). "Upregulation of vimentin is reported to contribute to liver fibrosis progression." (PMID 38243118, 2024). "The expression levels of various proteins, specifically PIK3CB, AKT, pAKT, HDAC3, HDAC6, MMP9, MMP2, VIM, and α-SMA, which are implicated in hepatocyte degeneration as well as the initiation and progression of liver fibrosis, were analyzed using Western blotting." (PMID 39683581, 2024). "Circulating levels of citrullinated and matrix metalloproteinases (MMP)-degraded vimentin (VICM) were increased in mouse liver tissues of hepatic fibrosis and in human liver tissues of early hepatic fibrosis associated with hepatitis c virus (HCV) and nonalcoholic fatty liver disease." (PMID 36832148, 2023). "Citrullination impairs vimentin filament assembly, which enhances the formation of soluble precursors that are transported extracellularly and that subsequently elicit autoimmune responses in joints affected by rheumatoid arthritis and in liver fibrosis." (PMID 35359446, 2022). "HJRG and silymarin can reduce the desmin and vimentin content of liver fibrosis rats (p < 0.05)." (PMID 35942372, 2022). "Although LX-2 cell line enjoys great popularity among researchers interested in the elucidation of mechanisms underlying stellate cell biology and liver fibrosis, it expresses a-SMA, vimentin, GFAP, and PDGFRb suggesting that cell line retains key features of activated/transdifferentiated HSC." (PMID 32887613, 2020). "Moreover, activated hepatic stellate cells under liver fibrosis are characterized by vimentin overexpression, indicating their mesenchymal phenotype." (PMID 32842595, 2020). "Again, the overexpressed vimentin was observed in the plasma samples derived from patients with hepatic fibrosis/cirrhosis, suggesting that vimentin may be a key factor in regulating the progression of liver fibrosis." (PMID 31581522, 2019). "During the EMT in hepatic fibrosis, intercellular junctions of epithelial cells are disrupted by downregulation of E-cadherin, which is confirmed by increase of mesenchymal phenotype, including vimentin." (PMID 30103395, 2018). "Our data indicted two SOX9-regulated ECM proteins, OPN and VIM have potential as biomarkers of liver fibrosis severity; interestingly, the data, for instance on AUROCs, were comparable to those from previous studies scrutinising other validated individual biomarkers and panels (reviewed in8)." (PMID 30559459, 2018). "Thus, we reveal that the VIM gene may play an important role in the immune response to liver fibrosis through o B cell activated Effector memory CD8 T-cell and mast cells." (PMID 36725885, 2023). "We used COL1A1 as the primary endpoint, but vimentin, TGF-β1, and α-SMA were also monitored to closely track the state of the HSCs when modelling liver fibrosis." (PMID 38228622, 2024). "Consistently, accelerated liver fibrosis development was identified by Sirius Red staining, α-SMA staining, Col1α1 staining, and Vimentin staining after overexpression of miR-144 in HSCs." (PMID 38725842, 2024). "VIM and S100A4 were upregulated in liver fibrosis but downregulated in IPF; we further collected mice fibrotic livers to examine their expression." (PMID 39257588, 2024).
liver fibrosis (continued). "Like VIM, THBS1 is a marker of liver fibrosis and cirrhosis with important roles in inflammation, cellular adhesion, growth, migration, and angiogenesis." (PMID 36768808, 2023). "RT-PCR and WB analyses indicated that liver fibrosis-related factors (including α-SMA, TGF-β1, TIMP-1, MMP-2, and Vimentin) were significantly downregulated, while E-cadherin was significantly upregulated in wild-type and αERKO mice after SSd treatment." (PMID 35694250, 2022). "Our in vitro results showed that silencing ARK5 in hepatocytes suppressed TGF-β1-induced upregulation of α-SMA and Vimentin expression, further suggesting that ARK5 mediates hepatocyte EMT during liver fibrosis." (PMID 36361872, 2022). "The expression of liver fibrosis markers including α-smooth muscle actin (α-SMA), collagen I, and vimentin were examined by immunohistochemistry and quantitative real-time polymerase chain reaction." (PMID 32245503, 2020). "Most studies suggest that HSC activation is the key pathological process to start hepatic fibrosis; α-SMA and vimentin are the marker proteins of HSC activation." (PMID 28246592, 2017). "Meanwhile, liver fibrosis, as assessed by smooth muscle actin (SMA), vimentin and Masson staining was significantly ameliorated by belnacasan treatment." (PMID 27924062, 2016). "Activated HSCs are identified by the overexpression of α-SMA and extreme expression of extra cellular matrix proteins (vimentin, β-catenin, and snail) through inflammatory cytokines such as TNF-α, IL-1β, and IL6, which increase the development of liver fibrosis." (PMID 37090196, 2023). "From the IHC staining, qRT-PCR, and western blot, the activation markers, including α-SMA, vimentin, Col I, and Col III, were up-regulated in the livers of CCl4-induced liver fibrosis mice than that in the control, which were further enhanced by the DSS exposure." (PMID 34603071, 2021). "Furthermore, the expression levels of liver fibrosis markers (α-SMA, collagen I, and Vimentin) were all significantly lower in BMSCs-HGF/UTMD group in comparison with other groups." (PMID 32245503, 2020). "Furthermore, MSCsmiRNA-181-5p-Exos significantly down-regulated expression of pro-fibrotic genes (collagen I, vimentin, α-SMA and fibronectin) in HSCs, which led to the attenuation of CCl4-induced liver fibrosis in MSCsmiRNA-181-5p-Exos-treated mice." (PMID 31835680, 2019). "Furthermore, through the production of TGF-β1, Kupffer cells induce enhanced expression of pro-fibrotic genes (collagen I, vimentin, α-SMA and fibronectin) in HSCs, resulting in the development of liver fibrosis." (PMID 31835680, 2019). "Combined with our own data in liver fibrosis and studies in other organs, we were able to further scrutinize these data to identify a cohort of highly expressed ECM proteins amenable to assay in patient serum samples, including OPN, VIM, SPARC, GPNMB and FN1." (PMID 30559459, 2018). "Other study reported that the serum concentration of anti-modified citrullinated vimentin (anti-MCV) antibodies was significantly higher in patients with hepatic fibrosis than in patients with no hepatic fibrosis." (PMID 30071078, 2018). "As we and many others have reported, here we used four different double labelling immunofluorescence methods to analyse the changes in TCs in human liver fibrosis, including double labelling for CD34 and PDGFR-α, CD34 and PDGFR-β, CD34 and vimentin, and CD34 and c-kit/CD117." (PMID 25661250, 2015). "The inhibition of Hh signaling pathway restored the expression of epithelial marker E-cadherin, repressed the expression of mesenchymal marker Vimentin and provoked the reversal of EMT to MET in CCl4-induced fibrotic liver tissue, which contributed to alleviating the degree of liver fibrosis." (PMID 25345787, 2014).
liver fibrosis (continued). "VIM is a type of intermediate filament protein that contributes to cell migration, adhesion, inflammation and apoptosis, and is found to be significantly upregulated in advanced liver fibrosis since it is expressed in a wide range of non-epithelial cells." (PMID 36768808, 2023). "Interestingly, GFAP was increased in activated HSCs and GFAP-expressing HSCs, and myofibroblasts accumulated in and around hepatic fibrosis, although vimentin was increased in hepatic fibrosis but not in activated HSCs." (PMID 30071078, 2018).
meningioma (55 papers, 2005 to 2026). A generally slow growing tumor attached to the dura mater. "Immunopositivity for EMA and vimentin in association with the imaging findings established the final diagnosis of meningioma." (PMID 22011733, 2011). "In addition, cytokeratin and vimentin intermediate filaments are present in many of the histologic variants of meningioma." (PMID 29983887, 2018). "Moreover, multiphosphorylated vimentin has been described to be associated to invasiveness in meningiomas, highlighting a potential role of vimentin phosphorylation in invasion." (PMID 24282534, 2013). "Accordingly, it can be hypothesized that excessive phosphorylation of vimentin, as a process leading to vimentin filament disassembly, may underlie important steps in migratory control of meningioma cells." (PMID 20169076, 2010). "Careful microscopic examination combined with immunohistochemical positivity for EMA and vimentin strongly supports the diagnosis of meningioma." (PMID 41210036, 2025). "EMA and vimentin are widely expressed in meningiomas and remain the principal lineage markers supporting meningothelial origin." (PMID 41552249, 2025). "The histopathological diagnosis of meningioma was reinforced with the positive labeling of vimentin (moderate to strong) and EMA (mild to moderate) in neoplastic cells in most cases, independently of its grade or subtype." (PMID 39453053, 2024). "The tumor cells stained positive for commonly observed meningioma markers like vimentin, reticulin, and cyclin D1." (PMID 39139315, 2024). "Histopathological diagnosis of meningioma was reinforced with the immune positivity to vimentin (moderate to strong) and EMA (mild to moderate) in neoplastic cells in most cases, independently of its grade or subtype." (PMID 39453053, 2024). "Most meningiomas express EMA with a decreased expression index in high-risk meningiomas (WHO grade 2 and 3) and vimentin is also present in the majority of cases of meningiomas, especially in high-risk ones (grade 2 and 3)." (PMID 39202270, 2024). "We interrogated our transcriptomic data set for the expression of two genes associated with meningiomas and EMT: VIM encoding for vimentin (mesenchymal) and CDH1 encoding for E-cadherin (epithelial)." (PMID 38102708, 2023). "Meningioma verification in the clinic depends primarily on HE histology and perhaps the immunohistochemical markers vimentin, epithelial membrane antigen (EMA), somatostatin receptor 2 (SSTR2), and Ki67/MIB-1." (PMID 37898750, 2023). "In both heterotopic and orthotopic approaches, transplantation of low-passage patient-derived tumor cells formed meningiomas positive for PR and vimentin." (PMID 38001599, 2023). "In order to investigate the extensive MIF-CD74 interactions in meningiomas, immunofluorescence staining was performed on five distinct types of meningiomas, including DAPI, MIF, CD74, and the meningioma marker Vimentin." (PMID 37880655, 2023). "The meningioma derived cells of the meningothelial subtype retained their characteristic morphology and expression of histopathological markers vimentin, desmoplakin, and epithelial membrane antigen (EMA) in co-culture." (PMID 36289516, 2022). "Immunohistochemical examination demonstrated that meningioma cells were positive for vimentin staining and they noted strong diffuse expression in 15 meningiomas they investigated." (PMID 33915799, 2021). "Ng and Wong inspected the use of immunohistochemistry Cryo-sections from 50 meningiomas of diverse histological subtypes and found vimentin positive in 98% of meningiomas." (PMID 33915799, 2021). "Our results showed that all the cancer cell lines expressed Vimentin, a meningioma marker, along with endogenous human telomerase catalytic subunit (hTERT)." (PMID 32742192, 2020). "In this study, all primary cell lines derived from benign and atypical meningioma retained the strong expression of the meningioma marker Vimentin, which has been explicitly related to tumor malignancy." (PMID 32742192, 2020).
meningioma (continued). "EMA and vimentin are important markers of meningioma cells, and these proteins were strongly expressed by tumour cells in all cases in the present study." (PMID 30419957, 2018). "For double-staining analysis, the most significant average count increase in grade II/III meningiomas was seen for Vimentin+FZD9+ (Brown–Forsythe ANOVA, P < 0.01)." (PMID 29849507, 2018). "All cell lines derived from KCI-MENG1 retained the expression of the meningioma diagnostic markers EMA and vimentin, which were weakly and strongly stained in the patient tumor specimen, respectively." (PMID 26174772, 2015). "For this study, we established primary meningioma cultures comprised of epithelial-like cells expressing vimentin, epithelial membrane antigen (EMA), and S100β, but not glial fibrillary astrocytic protein (GFAP)." (PMID 25247996, 2014). "Immunohistochemistry staining showed that tumor cells of meningioma were strongly immunoreactive for vimentin, epithelial membrane antigen, and progesterone receptor." (PMID 23198201, 2012). "The pathological findings and immunohistochemical features show a similar expression of EMA and vimentin, but S-100 protein is rarely expressed in meningiomas." (PMID 21320334, 2011). "This marker was purified and identified as a multiphosphorylated form of vimentin, a cytoskeletal protein expressed in meningiomas." (PMID 20169076, 2010). "Clinicopathological examination of meningioma has benefited from the discovery of several molecular markers such as vimentin and epithelial membrane antigen (EMA)." (PMID 20199689, 2010). "It is also worth mentioning that vimentin is one of the usual protein markers detected by immunohistochemistry for the definite diagnosis of meningiomas whatever their invasive or noninvasive phenotype is." (PMID 20169076, 2010). "We then immunodetected vimentin in meningioma tumor slices with a vimentin-directed monoclonal antibody." (PMID 20169076, 2010). "Our present data clearly illustrate that, in meningiomas that infiltrate bone or sinuses, the infiltrative behavior of these tumors correlates better with the level of phosphorylated vimentin than with the global expression level of this protein." (PMID 20169076, 2010). "Immunocytochemistry staining enables the distinction of atypical meningiomas from gliomas, neurogenic tumors, mesenchymal tumors, and some metastatic tumors with epithelial membrane antigen (EMA), with vimentin being the preferred diagnostic marker for meningiomas." (PMID 39202270, 2024). "Vimentin tested positive in some cases of feline meningiomas." (PMID 38137885, 2023). "The in silico pathway analysis was followed by validation of integrin-linked kinase (ILK) along with its associated pathway components, like ITGB1 and VIM, which are known to play important roles in regulating the EMO and EMT transmission responsible for the progression of meningioma." (PMID 37887327, 2023). "LMNA and VIM were found to be upregulated in high-grade meningioma for the peptides monitored." (PMID 37887327, 2023). "However, subcutaneous injection of high-passage cells yielded PR-negative and vimentin-positive tumors, consistent with high-grade meningiomas." (PMID 38001599, 2023). "Furthermore, M2-MDEs facilitated the upregulation of vimentin, N-cadherin, slug, and snail in meningioma, suggesting that M2-MDEs contribute to the mesenchymal transition of meningioma cells." (PMID 35637794, 2022). "For the meningioma tissue samples, we observed overexpression of VIM, CST3 and CLU." (PMID 34055594, 2021). "However, consistent with published data, a higher number of positive cells stained for Ki67 and Vimentin were detected in grade II/III compared with grade I meningiomas." (PMID 29849507, 2018).